HMGB1 (high mobility group box 1)
Diseases named in the same sentence as HMGB1 in open-access papers (continued):
Sharing a sentence is not in itself a finding about the gene and the disease.
bladder cancer (continued). "Our findings align with previous research wherein, in a mouse bladder cancer model receiving radiation therapy, NETs were found to promote their formation through the protein HMGB1 via a TLR4-dependent pathway both in vitro and in vivo." (PMID 38699144, 2024). "We further reveal that IGF2BP3 enhances the advancement of bladder cancer by stabilizing the mRNA of HMGB1." (PMID 38504159, 2024). "Irradiated colorectal tumor cells stimulate non-irradiated tumor cell proliferation when co-cultured through HMGB1, while in bladder cancer, HMGB1 was connected with radioresistance, in vitro and in vivo, through the upregulation of autophagy." (PMID 36982351, 2023). "UCA1 by regulating the high mobility group box 1 (HMGB1) pathway enhances the properties of bladder cancer invasion and metastasis." (PMID 36685879, 2022). "In this study, we illustrated a novel upstream mechanism regulating the expression of HMGB1 in bladder cancer cells in vitro and in vivo." (PMID 31848324, 2019). "Radiation therapy induces the release of the alarmin protein HMGB1 both in-vitro and in-vivo in a bladder cancer model." (PMID 31015520, 2019). "In order to study the role of extracellular HMGB1 in bladder cancer radio-resistance, we first validated MB49 cell line expression and release of HMGB1 after radiation both in-vitro and in-vivo." (PMID 31015520, 2019). "High mobility group box-1 (HMGB1) was shown to play a role in bladder cancer radioresistance through its intracellular functions in promoting DNA damage repair and autophagy." (PMID 31015520, 2019). "In summary, in this study we identify a novel mechanism of radioresistance in bladder cancer mediated by the immunological functions of extracellular HMGB1." (PMID 31015520, 2019). "Our novel findings demonstrate that extracellular HMGB1 is involved in immune-mediated radio-resistance of bladder cancer." (PMID 31015520, 2019). "CVA21 destruction of susceptible bladder cancer cell lines induces immunogenic cell death, as indicated by the markers endo-calreticulin and HMGB1 (high mobility group box-1) protein." (PMID 31100962, 2019). "We then sought to investigate the mechanisms by which extracellular HMGB1 is mediating radioresistance of bladder cancer." (PMID 31015520, 2019). "Patients with bladder cancer featuring high HMGB1 expression have shorter disease-free survival and overall survival." (PMID 31848324, 2019). "We conclude that extracellular HMGB1 is involved in bladder cancer radioresistance through promoting pro-tumor immune mechanisms." (PMID 31015520, 2019). "Extracellular HMGB1 is involved in radioresistance of bladder cancer as indicated by the radiosensitization effect observed after the combination of radiation and GLZ." (PMID 31015520, 2019). "We identified a novel mechanism of bladder cancer radioresistance mediated by the immunological functions of HMGB1." (PMID 31015520, 2019). "HMGB1 was identified as a direct target gene of miR-496 in bladder cancer, and HMGB1 expression was enhanced by NNT-AS1 via sponging of miR-496." (PMID 31848324, 2019). "HMGB1 exerts oncogenic effects on the formation and progression of bladder cancer and participates in the modulation of tumor cell proliferation, apoptosis, cell cycle, metastasis, radioresistance, and tumorigenesis." (PMID 31848324, 2019). "Collectively, these data suggested that HMGB1 mRNA is a direct target of miR-496 in bladder cancer cells." (PMID 31848324, 2019). "In our study, for the first time, miR-496 was found to be downregulated in bladder cancer and to directly target HMGB1 mRNA to restrain the aggressive phenotype of bladder cancer." (PMID 31848324, 2019). "In bladder cancer cells, the amount of DNA damage induced by radiotherapy was increased by more than twofold, that enhancing cell sensitivity to radiotherapy, when HMGB1 was knocked down." (PMID 30157958, 2018).
bladder cancer (continued). "The expression level of TUG1 and HMGB1 mRNA and protein was about twice higher in bladder cancer tissues than that in adjacent normal tissues." (PMID 28376901, 2017). "Taken together, all these results revealed that radiation treatment promotes the TUG1 and HMGB1 expression in bladder cancer cell lines." (PMID 28376901, 2017). "Downregulation of TUG1 enhanced the radiosensitivity of bladder cancer cells via inhibiting HMGB1 expression." (PMID 28376901, 2017). "HMGB1 expression was increased in primary bladder cancer tissue and GEM-treated bladder cancer cells." (PMID 29069735, 2017). "All these results illustrated that silencing of TUG1 inhibited the HMGB1 expression in bladder cancer cell lines." (PMID 28376901, 2017). "These experiments suggest that while GEM kills bladder cancer cells through apoptosis, it also increases HMGB1 expression and induces autophagy." (PMID 29069735, 2017). "In consistent with our surmise, our findings reveal that IncRNA TUG1 knockdown enhances radiosensitivity of bladder cancer through suppressing HMGB1 expression." (PMID 28376901, 2017). "While gemcitabine induced apoptotic cell death, it also induced HMGB1 expression and autophagy in bladder cancer T24 and BIU-87 cells." (PMID 29069735, 2017). "Compared to control groups, siRNA-3 transfection suppressed cell viability, suggesting that HMGB1 is involved in cell viability in bladder cancer cells." (PMID 29069735, 2017). "Quantitative real-time PCR (qRT-PCR) was conducted to measure the expression of TUG1 and HMGB1 mRNA in bladder cancer tissues and cell lines." (PMID 28376901, 2017). "Research indicates that HMGB1 modulates key cellular mechanisms, including programmed cell death and proliferation, thereby influencing the proliferative capacity and metastatic potential of bladder cancer cells." (PMID 40969278, 2025). "Given the association of HMGB1 with the inflammatory response and immune microenvironment, our study aimed to explore the relationship between the IGF2BP3 level and the immune response in bladder cancer." (PMID 38504159, 2024). "Collectively, our results indicate that IGF2BP3 promotes HMGB1 stability by directly binding to HMGB1 mRNA through m6A modification in bladder cancer cells and suggest a potential role for IGF2BP3 in modulating the immune response in BLCA and its impact on immunotherapy efficacy." (PMID 38504159, 2024). "Combining the results of bladder cancer cell apoptosis, HMGB1 protein expression, and chemokine CCL21 secretion in this paper, it can be hypothesized that BT-B cells received the highest radiation dose of 10 Gy have the maximal effect on imDC." (PMID 39231199, 2024). "After HMGB1 knockdown, the radiosensitivity of bladder cancer cells was increased." (PMID 35812184, 2022). "We then tested the hypothesis that HMGB1 is involved in bladder cancer radio-resistance through its extracellular functions." (PMID 31015520, 2019). "In the current study, we hypothesized that XRT-induced HMGB1 in the microenvironment of bladder cancer dictates the nature of the immune response and the outcome of the tumor." (PMID 31015520, 2019). "Targeting HMGB1 could serve as a novel therapeutic approach to overcome radiation resistance in bladder cancer." (PMID 31015520, 2019). "In order to unravel the mechanisms behind the radiosensitization effect of HMGB1 inhibition in bladder cancer, we hypothesized that extracellular HMGB1 was mediating radioresistance through its immunological functions." (PMID 31015520, 2019). "Furthermore, we found that HMGB1 mRNA was more strongly expressed in bladder cancer tissues than in ANTs (P < 0.05)." (PMID 31848324, 2019). "Thus, miR-496 was confirmed as a tumor-suppressive miRNA inhibiting the malignant characteristics of bladder cancer cells at least partly by decreasing HMGB1 expression." (PMID 31848324, 2019). "LncRNA TUG1 knockdown enhances radiosensitivity of bladder cancer by suppressing HMGB1 expression." (PMID 28376901, 2017).
bladder cancer (continued). "While GEM kills bladder cancer cells through apoptosis, it also induces a cytoprotective autophagy involving HMGB1-mediated JNK and ERK activation, and targeting this pathway may improve the anticancer efficacy of gemcitabine against bladder cancer." (PMID 29069735, 2017). "This study provides evidence showing that HMGB1 mediates autophagy to attenuate GEM-induced apoptotic death in bladder cancer cells, which may play a role in gemcitabine resistance." (PMID 29069735, 2017). "HMGB1 was found to be overexpressed and could regulate tumor growth, metastasis and survival in cancers, including bladder cancer." (PMID 28376901, 2017). "Furthermore, our findings suggest that TUG1 knockdown enhances radiosensitivity of bladder cancer cells in vivo and in vitro by suppressing the expression of HMGB1." (PMID 28376901, 2017). "The levels of TUG1 and HMGB1 were remarkably increased in bladder cancer tissues and cell lines." (PMID 28376901, 2017). "We found that HMGB1 is overexpressed in human bladder cancers with different stages and grades." (PMID 29069735, 2017). "However, the function of HMGB1 in bladder cancer carcinogenesis and radioresistance remains poorly understood." (PMID 28376901, 2017). "Furthermore, overexpression of HMGB1 reversed TUG1 knockdown-induced effect in bladder cancer cells." (PMID 28376901, 2017). "In addition, HMGB1 accelerates the transition of the uroepithelial cancer cell cycle from G to S1 phase by promoting the expression of cell cycle protein A, which promotes the growth of bladder cancer." (PMID 40969278, 2025). "Thus, HMGB1 serves as an effective early indicator for predicting the prognosis of patients with bladder cancer, and at the same time, inhibition of HMGB1 may enable bladder cancer patients to obtain greater benefits from systemic therapy." (PMID 40969278, 2025). "Also, NEAT1 was reported conductive to the bladder cancer progression by the miR-410/HMGB1 axis." (PMID 32280304, 2020). "In addition, HMGB1 has been confirmed as an independent prognostic factor in bladder cancer." (PMID 31848324, 2019). "Moreover, the level of TUG1 is positively related to HMGB1 expression in bladder cancer tissues." (PMID 28376901, 2017). "Moreover, HMGB1 knockdown markedly sensitize the bladder cancer cells to radiotherapy." (PMID 28376901, 2017). "Thus, we investigated HMGB1 is involved GEM-induced autophagy in bladder cancer cells." (PMID 29069735, 2017). "Therefore, we explored whether TUG1 regulated the radiosensitivity of bladder cancer through modulating HMGB1 expression." (PMID 28376901, 2017). "Firstly, fluid-based measurements—notably urinary HMGB1 and urinary VEGF in bladder cancer and serum or tissue assessments of GDF15, HSP90, and S100A9 in renal tumors—provide viable, minimally invasive opportunities to complement imaging and histopathology." (PMID 41009692, 2025). "Given the involvement of HMGB1 in the inflammatory response, tumorigenesis, and allograft rejection, and its contribution to the progression of bladder cancer, we investigated the relationship between IGF2BP3 and HMGB1." (PMID 38504159, 2024). "HMGB1 acts as an EMT inducer in many human cancer cells and is significantly upregulated higher in bladder cancer cells than in normal urothelial cells." (PMID 36685879, 2022). "Bladder cancer tumors developed after injection of MB49 cells into C57BL/6 mice were collected and stained for HMGB1 by immunofluorescence." (PMID 31015520, 2019). "Together with the results from the HMGB1 knockdown experiments, these data strongly suggest that HMGB1 mediates GEM-induced cytoprotective autophagy to blunt GEM's cytotoxicity in bladder cancer cells." (PMID 29069735, 2017). "Suppressing HMGB1 expression attenuated autophagy and potently enhanced apoptosis in GEM-treated bladder cancer cells." (PMID 29069735, 2017). "Thus, we investigated whether GEM affects HMGB1 expression in bladder cancer cells." (PMID 29069735, 2017).
bladder cancer (continued). "HMGB1 expression was induced by GEM, and HMGB1 knockdown promoted GEM's cytotoxicity in bladder cancer cells." (PMID 29069735, 2017). "Collectively, these results suggest that HMGB1 mediates GEM-induced JNK and ERK for autophagy activation in bladder cancer cells." (PMID 29069735, 2017). "In this review, we focus on describing the emerging evidence for GDF15, VEGF, TGF-β1, HSP90, HMGB1, and S100A9 as candidate biomarkers across renal and bladder cancers—highlighting their biological rationales, analytical performance characteristics, and prospective roles in clinical practice." (PMID 41009692, 2025). "Importantly, pharmacological inhibition of HMGB1 with glycyrrhizin, a specific HMGB1 inhibitor, effectively reversed the cancer-promoting effects of IGF2BP3 overexpression in bladder cancer." (PMID 38504159, 2024). "In bladder cancer, it has been proved that the silencing of lncRNA Taurine-upregulated gene 1 (TUG1) improves radiation sensitivity by inhibiting HMGB1 expression, resulting in less cell proliferation, more cell apoptosis and decreased colony survival in bladder cancer cell lines under radiation." (PMID 32122355, 2020). "The high expression of HMGB1 showed a negative correlation with miR-496 expression among the 47 bladder cancer tissue specimens (r = -0.5221, P = 0.0002)." (PMID 31848324, 2019). "In this report, HMGB1 expression was found to be increased in 30 primary bladder cancer tissue specimens compared to their matched adjacent non-tumor tissues." (PMID 29069735, 2017). "The expression of TUG1 and HMGB1 mRNA was measured by qRT-PCR and the HMGB1 protein level was determined by western blot in bladder cancer tissues and adjacent non-cancer tissues, respectively." (PMID 28376901, 2017). "HMGB1 and HMGB2 are the main members of the HMGB protein family and their overexpression has been observed in numerous human malignancies, including hepatocellular, skin squamous cell, prostate, gastrointestinal breast, and bladder carcinomas." (PMID 24479488, 2014). "Recently, extracellular HMGB1 was established to bind with RAGE, stimulate the development of drug resistance after chemotherapy and regulate autophagy and apoptosis in neighboring tumor cells; the protein has also been proposed as a non-invasive marker for the detection of bladder carcinoma." (PMID 37880798, 2023). "However, the clinicopathological significance of HMGB1 and HMGB2 expression in bladder carcinoma (BCa), particularly the involvement of these proteins in angiogenesis, remains unclear." (PMID 23426143, 2013). "However, the role of extracellular HMGB1 in bladder cancer radio-resistance has never been studied." (PMID 31015520, 2019). "Thus, our results suggest that while gemcitabine kills bladder cancer cells through apoptosis, it also induces a cytoprotective autophagy involving HMGB1-mediated JNK and ERK activation, and targeting this pathway may improve the anticancer efficacy of gemcitabine against bladder cancer." (PMID 29069735, 2017). "Furthermore, we identified a novel pathway consists of HMGB1, ERK, JNK and Bcl-2 for GEM-induced cytoprotective autophagy, and intervention targeting this pathway may improve the anticancer activity of GEM against bladder cancer." (PMID 29069735, 2017). "Our western blot results suggest that glucose deprivation in normoxic conditions also stimulates the release of HMGB1 from cancer cell lines MCF-7 (breast) and A549 (lung), but not from EJ138 bladder cancer cells." (PMID 26979829, 2016).
Parkinson disease (42 papers, 2013 to 2026). A progressive degenerative disorder of the central nervous system characterized by loss of dopamine producing neurons in the substantia nigra and the presence of Lewy bodies in the substantia nigra and locus coeruleus. "Similarly, in Parkinson’s disease, HMGB1 is associated with the aggregation of α-synuclein, enhancing inflammatory signaling and further worsening neurodegeneration and motor function loss." (PMID 39507236, 2024). "In multiple disorders, high levels of circulating HMGB1 act as a general biomarker that correlates with disease severity in diseases such as Parkinson's, autism, multiple sclerosis, and amyotrophic lateral sclerosis." (PMID 39158383, 2024). "In Parkinson’s disease, HMGB1 binds to aggregated α-synuclein in Lewy bodies and play a crucial role in augmenting chronic neurodegeneration." (PMID 39682695, 2024). "The same anti-HMGB1 mAbs have also elicit neuroprotective functions in treating neuropathic pain and Parkinson’s disease." (PMID 39682695, 2024). "Anti-HMGB1 impacts several central nervous system pathological conditions, such as Parkinson disease, traumatic brain injury, stroke, and spinal cord injury." (PMID 36310854, 2022). "In Parkinson's disease, HMGB1 specifically binds to α-syn aggregated in LBs isolated from rat brain, suggesting a promoting role of HMGB1 in neurodegenerative processes in the chronic phase of the disease." (PMID 36388178, 2022). "In a 1-methyl-4-phenyl-1,2,3,6-tetrahydropyridine (MPTP)-induced mouse model of acute Parkinson's disease, HMGB1 can promote the expression of tyrosine hydroxylase (TH) in the striatum, thereby maintaining dopaminergic neuron function." (PMID 36388178, 2022). "In modeled animals, the anti-HMGB1 monoclonal antibody (mAb) has also been proven to be useful for the treatment of a variety of CNS illnesses, notably hemorrhage, brain trauma, Parkinson's disease and Alzheimer's disease." (PMID 36310854, 2022). "It is noteworthy that anti-HMGB1 antibody has recently been found to exert neuroprotection in a rat model of Parkinson's disease." (PMID 27242399, 2016). "It was also demonstrated that HMGB1 provides the link between chronic neuroinflammation and progressive neurodegeneration in neurodegenerative diseases, such as Parkinson's disease." (PMID 23766563, 2013). "In a rotenone-induced experimental model of Parkinson’s disease (PD), agmatine also reduced the levels of HMGB1, the receptor for advanced glycation end products (RAGE), TLR4, and of the proinflammatory cytokines TNF-α and IL-1β in the substantia nigra pars compacta (SNpc) of rats." (PMID 38474387, 2024). "Also, high mobility group box 1 (HMGB1), a mammalian homolog of DSP1, is associated with several neurodegenerative diseases, including Parkinson’s disease (PD), Multiple Sclerosis (MS), and Amyotrophic lateral sclerosis (ALS)." (PMID 39003465, 2024). "In neurodegenerative diseases like Alzheimer’s and Parkinson’s, HMGB1 release from dying neurons may activate microglia and propagate sustained inflammation that drives progressive neurodegeneration." (PMID 38708343, 2024). "Several studies have shown the role of HMGB1 in Parkinson’s disease with respect to dopaminergic neuronal cell death in animal models and, in this context, anti-HMGB1 treatments show a positive response and demonstrate the protective effect on neuronal cell death and blood–brain barrier disruption." (PMID 37048161, 2023). "Recently, it was demonstrated that HMGB1 is the main mediator bridging persistent neuroinflammation and chronic progressive dopaminergic neurodegeneration in neurodegenerative diseases, such as Parkinson's disease." (PMID 24733965, 2014). "In addition, agents effective in blocking HMGB1/TLR4/NF-κB signaling have proven protective in animal models of Parkinson’s disease and could be useful in the treatment of AUD." (PMID 37626919, 2023).